SLC8A1-AS1 (SLC8A1 antisense RNA 1)
Gene: Long non-coding RNA gene on chromosome 2 (39,786,453 to 40,255,209, forward strand). Ensembl gene ENSG00000227028.
Diseases named in the same sentence as SLC8A1-AS1 in open-access papers:
SLC8A1-AS1 is named in the same sentence as 1 disease in open-access papers, as found by Europe PMC text mining. Sharing a sentence is not in itself a finding about the gene and the disease.
SLC8A1-AS1 shares sentences with these, for which no sentence is quoted: papillary thyroid cancer (1 paper).